EPHA3 (EPH receptor A3)
Diseases named in the same sentence as EPHA3 in open-access papers (continued):
Sharing a sentence is not in itself a finding about the gene and the disease.
tumor (continued). "EphA3 is also expressed in a wide range of epithelial tumors, often as part of the tumor microenvironment (TME), particularly in the mesenchymal-derived stromal and vascular tissues supporting the tumor, and in some myeloid-derived immune cell subtypes." (PMID 32397088, 2020). "It is imperative that by targeting the EphA3, EphA2, and EphB2 receptors at once, we will be targeting not just the tumor cells, but also key components within the GBM microenvironment that allow GBM to sustain and grow." (PMID 32340173, 2020). "We also detected abundant αDG expression in vimentin+, EphA3+, GFAPlow MES-like tumour regions." (PMID 31463571, 2019). "To examine if this same mechanism was operative in patient tissue and not an artefact of culture we assessed sequential (#1–4) GS tumour sections by IHC for αDG, EphA3, GFAP, pERK and Ki67." (PMID 31463571, 2019). "These regions were smaller and less prominent than in GS tumours, and also showed heterogeneous expression of GFAP, vimentin, EphA2, EphA3 αDG, CD49f and CD31, indicating that this tumour tissue patterning might also occur in GBM (Online Resource 2b)." (PMID 31463571, 2019). "A robust anti-tumour response, with no toxicity, was observed using EphA3, ADC, and RIT approaches, leading to a significant increase in overall survival." (PMID 30562956, 2018). "Brain uptake studies, using positron emission tomography/computed tomography (PET/CT) imaging, show EphA3 antibodies are effectively delivered across the blood-tumour barrier and accumulate at the tumour site with no observed normal brain reactivity." (PMID 30562956, 2018). "Furthermore, ANGPLT4 played a critical role in regulating tumor cell proliferation and angiogenesis, possibly by regulating STC1, EPHA3 and TNFSF14 genes." (PMID 28903395, 2017). "EphA3 was largely present in scattered areas within the tumor and of the invading ring, but not in the contralateral side." (PMID 27494882, 2016). "Despite convincing data suggesting a tumor suppressor role for EPHA3 during lung tumor progression, thus far no studies have addressed its in vivo functional role." (PMID 25713296, 2015). "EphA3 was also undetectable in various cultured endothelial cell lines, including human umbilical vein vascular endothelial cells (HUVECs), dermal microvascular endothelial cells (d-MVEC), and tumour-derived endothelial cells (TECs)." (PMID 25420155, 2014). "We observed EphA3 protein expression by stellate-like cells within normal, human BM and in the tumor stroma of human bone metastasis, but not in bone or other BM stromal cells." (PMID 25485970, 2014). "In most cases (37/43 genes), methylation was more frequent in cell lines than primary tumours, however for 6 genes this pattern was reversed (ZNF215: 21% and 42% respectively, DAPK1: 4% and 39%, EPHA3 13% and 32%, SMARCB1: 8% and 27%, EPS8 4% and 21% and MCM2: 0% and 21%)." (PMID 19493342, 2009). "The expression levels of EphA3, A4, A5, A7, A8, B1 and B4 and of ephrin A2, A3, A4, B2 were relatively low in both normal and tumour samples and these genes were not considered further." (PMID 16737551, 2006). "The IIIA4 mAb specifically binds EphA3+ tumour xenografts but not normal tissues." (PMID 36830852, 2023). "Of note, the direction of tumor progression from an initial KRAS mutation appears to dictate subsequent prognosis: median OS is 12 months vs not reached in KRAS to SMARCA4 and KRAS to EPHA3 groups, respectively." (PMID 37749078, 2023). "Using syngeneic mouse tumour allografts of EphA3-negative LLC cells implanted in these mice, we show that EphA3 expression is detectable in the MSC/CAF-like cells of the tumour microenvironment, and that knockdown of EphA3 expression indeed has impacts on tumour growth." (PMID 37760615, 2023).
tumor (continued). "EphA3 was expressed in the stromal and vascular tissues of human tumours and prostate mouse xenografts, where its treatment with anti-EphA3 mAb IIIA4 inhibited tumour growth, suggesting EphA3 as a novel target for the selective targeting of the tumour microenvironment." (PMID 36830852, 2023). "Despite the EphA3-related molecular alterations associated with IL-26 alone, treatment with IL-26 alone did not alter TNBC growth; rather, the effect of IL-26 on TNBC tumor growth was seen in the setting of EGFR-TKI exposure with an increased ER stress response." (PMID 34021125, 2021). "EphA3 targeted [64Cu]Cu-IIIA4 PET/CT imaging revealed specific tumor uptake in an orthotopic GB model and IIIA4 conjugated to maytansine induced a potent GB anti-tumor response." (PMID 34209513, 2021). "Another Eph receptor, EphA3, is overexpressed in almost 60% of GBM patient samples with increased presence in tumor initiating and infiltrating cells both in glioma and leukemia, invasive rings, and scattered areas within the tumor and niches close to the blood vessels." (PMID 30366424, 2018). "Furthermore, analysis of histopathology and NKX2-1 and tumor protein 63 (p63) biomarker expression to respectively depict ADC and SCC tissue, showed that constitutive absence of EphA3 did not alter the tumor histology." (PMID 25713296, 2015). "An anti-EphA3 antibody–drug conjugate (ADC) based on the IIIA4 mAb attached to the microtubule antagonist maytansine (IIIA4-USAN) proved successful in eliminating GBM cells in vitro and inhibiting development of several GBM tumour types in mice compared to the naked antibody." (PMID 36830852, 2023). "Based on our results, we concluded that EphA2, EphA3, EphA4, and EphA5 were down-regulated in BCs, and high expression levels of these genes indicated better RFS, suggesting that EphA2, EphA3, EphA4, and EphA5 act as tumor suppressors in BC and could be new biomarkers for its prognosis." (PMID 34221956, 2021). "An ADC directed against EphA3 based on the IIIA4 mAb, and utilizing the microtubule inhibitor maytansine (IIIA4-USAN), was highly effective in killing GBM cells in vitro, and potently inhibited growth of multiple GBM tumor models in mice, where the naked antibody had little effect." (PMID 32397088, 2020). "The rechallenge experiments provide compelling evidence of the recall function of EphA3 CAR T cells, with a notable percentage of mice exhibiting tumor clearance on secondary tumor implantation without further CAR T cell treatment." (PMID 39111833, 2024).
cancer (63 papers, 2009 to 2025). A tumor composed of atypical neoplastic, often pleomorphic cells that invade other tissues. "EphA3 is also the most highly mutated Eph receptor, and many EphA3 mutations identified in cancers impair kinase activity." (PMID 38811954, 2024). "An illustration of this was found in the close association between EphA3 expression and elevated stromal score across diverse cancers, whereas EphA10 expression demonstrated an inverse pattern." (PMID 38952552, 2024). "Mutations and altered expression of EphA3 have been associated with various human cancers, such as colorectal and lung carcinomas, in which EphA3 dysfunction correlates with poor prognosis and decreased survival." (PMID 37813891, 2023). "The clinical significance of EphA3 was explored in the TCGA cohort of patients through the survivALL package, whereas the pro-migratory role of EphA3 signaling was ascertained in both BC cells and cancer-associated fibroblasts (CAFs)." (PMID 37434266, 2023). "EPHA3 expression is positively associated with macrophages and cytotoxic cells, which consist of important elements in anti-cancer therapies." (PMID 36765579, 2023). "As EphA3 likely plays a role in cancer malignancy, there is considerable interest in understanding the mechanisms underlying EphA3 structure and function." (PMID 25993310, 2015). "EPHA3 was revealed as mutated in this cancer by DNA exome sequencing and RNASeq." (PMID 25861239, 2015). "Of these kinases, MAP2K1, OXSR1 and EPHA3 are implicated in cancer." (PMID 22219723, 2011). "The Ephrin receptor, EPHA3, functions in development and stem cell maintenance and can promote tumorigenesis in diverse cancers." (PMID 40869130, 2025). "Ifabotuzumab selectively binds to EphA3-positive cancer cells and can stimulate antibody-dependent cell-mediated cytotoxicity (ADCC)." (PMID 40688499, 2025). "Within the ‘Cancer hotspots database’, 18 variants were also present in our cohort, mainly missense, with stop-gained variants observed in RNF43 and EPHA3." (PMID 41294844, 2025). "We found that four genes (EPHA3, PDGFB, PDGFRB, and GNG2) are implicated in cancer cell migration, invasion, and angiogenesis." (PMID 38233802, 2024). "EphA3, a member of the Eph family of receptors, has been found to be overexpressed in several cancers with roles in oncogenesis, poor survival, and response to therapies." (PMID 36046842, 2022). "The coexpression of Ephrin-A3 can block the ability of EphA2 and EphA3 to link ephrins in trans and become activated, while Ephrin-B2 can deter not only EphB4 but also EphA3 in the cancer cells." (PMID 32368295, 2020). "The overexpression of EphA3 has been demonstrated in different cancers, such as lung cancers, melanomas, gastric carcinoma, leukemia, in B and T cell malignancies and in glioblastoma multiforme." (PMID 28415715, 2017). "Not only were EphA3 protein levels increased in tumorspheres, we also observed a high degree of co-staining with the cancer stem cell marker Nestin in situ." (PMID 27494882, 2016). "This information will help elucidate the role of EphA3 in cancer cells, which is poorly understood, and design strategies to target EphA3 for cancer treatment." (PMID 25993310, 2015). "This study highlights the importance of creating appropriate model systems to study the in vivo functional relevance of putative cancer drivers, such as EPHA3." (PMID 25713296, 2015). "Among the Eph receptors, EphA2 and EphB4 are the most widely expressed in epithelial and cancer cells, although most other Eph receptors including EphA3 are also aberrantly expressed in at least some cancers." (PMID 24348920, 2013). "Here we show that in cancer cells, coexpressed ephrin-A3 can inhibit the ability of EphA2 and EphA3 to bind ephrins in trans and become activated, while ephrin-B2 can inhibit not only EphB4 but also EphA3." (PMID 24348920, 2013).
cancer (continued). "We find that somatic mutations create or disrupt putative miRNA target sites in the 3′UTRs of many genes, including several genes, such as MITF, EPHA3, TAL1, SCG3, and GSDMA, which have been previously associated with cancer." (PMID 23091610, 2012). "Developing a class-switched and defucosylated version of Ea3Mab-20 could improve its therapeutic efficacy against EphA3-positive cancers in preclinical research." (PMID 40688499, 2025). "•EphA3 represents a promising target for antibody-based cancer therapy and diagnosis." (PMID 40688499, 2025). "Our study reveals the anti-cancer role of EPHA3 and its potential value in immunotherapy." (PMID 36765579, 2023). "The newly detected interaction between PD-L1 and EPHA3 is particularly interesting, as it may have implications for cancer therapy." (PMID 38098892, 2023). "Previous investigations have showed that EphA3 has different roles in different cancers." (PMID 36578556, 2022). "EPHA3 is a promising therapeutic target in cancer, including in glioblastoma." (PMID 34359759, 2021). "EphA3 is a member of the Eph family of cell-surface receptor tyrosine kinases which, with their ephrin ligands, can modulate cell adhesive properties as well as coordinate cell movement, and play critical roles in development, tissue homeostasis, and cancer." (PMID 34359759, 2021). "Other studies that demonstrate upregulation of ephrin-A3 in NSCLC and inhibitory effects of ephrin-A3 and ephrin-B2 on transactivation of EphA2/EphA3 and EphA3/EphB4, respectively, are indicative of context-dependent aberrations of Eph/ephrin molecules in cancer cells." (PMID 29682554, 2018). "Interestingly, we found five upregulated cancer-related genes (Epha3, Hjurp, Kif26, S1pr3 and Pde3B) that shared miRNAs with the HMGA1P7 transcript." (PMID 25268743, 2014). "We have detected inhibitory cis interactions with ephrins in cancer cells not only for EphA3, which had been previously studied in neurons, but also for endogenous EphA2 and EphB4, for which the effects of cis interactions have not been previously investigated." (PMID 24348920, 2013). "Some of the mutated genes, including the tyrosine kinases EPHA3 and EPHB2, are clearly amenable to pharmacological intervention and could represent novel therapeutic targets for these incurable cancers." (PMID 20838624, 2010). "Therefore, the role of EPHA3 in cancers presents context dependence." (PMID 36578556, 2022). "Considering the experimental therapies targeting Eph and myosin in nerve regeneration and cancer pathologies, it is conceivable that a better understanding of the PS/γ-secretase/EphA3/NMIIA crosstalk may provide new perspectives on common mechanisms regulating human brain development and diseases." (PMID 31577226, 2019). "An EPHA3 monoclonal antibody, KB004, had already entered clinical trials for patients with glioblastoma and advanced hematologic malignancies before this interaction was discovered." (PMID 38098892, 2023). "Four of these genes (PCGME1, PEG3, EPHA3, and EFNB2) are of particular interest as they are known to modulate cancer cell proliferation and/or survival." (PMID 28035996, 2016). "Growing evidence indicates that the signaling proteins of EPHA3 downstream, including PI3K, BMX and STAT3, play crucial roles in tumorigenesis and cancer progression." (PMID 27101199, 2016). "Two genes in this pathway, EPHA3 and FRS2, were designated SCNA-genes in both our dataset and in Stark and Hayward, and were annotated as amplified, in skin-derived tumors, in the Cancer Genome Project dataset." (PMID 21494657, 2011). "Direct EphA3 targeting in the form of small molecule kinase inhibitors and monoclonal antibodies have progressed to early phase clinical trials both in hematological and solid (GBM) cancers." (PMID 36046842, 2022). "EPHA3, a member of the EPH family, is overexpressed in various cancers." (PMID 33919657, 2021).
cancer (continued). "In contrast, in primary PCa, cancer cells of all neoplastic acini are invariably EPHA3 negative, with no modification of the staining pattern in the stroma compartment." (PMID 25485970, 2014). "We have shown that the levels of EphA3 on the cancer cell surface are not decreased by coexpression of ephrin-A3." (PMID 24348920, 2013). "These genes were not included in our original dataset either because they were not in the "Cancer Gene Census" category of COSMIC (MMP2, PIK3C3, TGM3, EPHA3) or because there was no crystal structure available (DCLK3)." (PMID 21575214, 2011).
hematologic malignancies (6 papers, 2020 to 2024). "In a related publication using the same EphA3-targeted clone as a monoclonal antibody in advanced hematological malignancies demonstrated mild and transient toxicities." (PMID 39111833, 2024). "We found that high expression of SEC61A1 was associated with upregulation of EPHA3, MMP7, BIRC7, and ROS1, all of which have been reported as prognostic markers or therapeutic targets in hematological malignancies." (PMID 38584833, 2024). "A humanized afucosylated version of the EphA3 antibody IIIA4 (Ifabotuzumab/KB004) was also investigated in a clinical trial (NCT01211691) in patients with EphA3-expressing hematologic malignancies." (PMID 32397088, 2020). "Additionally, EphA3, often overexpressed in hematologic malignancies, has been targeted by the humaneered derivative of the IIIA4 anti-EphA3 mAb (KB004) in clinical trials for hematological malignancies." (PMID 38811954, 2024).
infection (4 papers, 2015 to 2024). The state of being infected such as from the introduction of a foreign agent such as serum, vaccine, antigenic substance or organism. "Further studies, including groups of uninfected control animals, should particularly focus on the expressions of GBP7, RFK, IRF4, and EPHA3 at several time points following infection." (PMID 33918448, 2021). "However, upon infection with HA.EPHA3 lentiviral particles, PC-3 had robust EphA3 expression, which was detected by both EphA3 and HA-tag antibodies in a western blotting experiment." (PMID 35324780, 2022).
adenocarcinoma (2 papers, 2011 to 2015). A common cancer characterized by the presence of malignant glandular cells.
CNS tumors (1 paper, 2024). "Collectively these data suggest that there is a subpopulation of patients across CNS tumors whereby targeting EphA3 with a CAR may have clinical benefit." (PMID 39111833, 2024).
neurological disorders (1 paper, 2019). "Additionally, genes previously associated with neurological disorders were similarly up regulated, such as Mdga2, Clu, Epha3, Chl1, Cntn4, Cdh23, and Pard3b." (PMID 30628890, 2019).
EPHA3 also shares sentences with these, for which no sentence is quoted: oligodendroglioma (3 papers); ovarian carcinoma (3); idiopathic pulmonary fibrosis (2); neuroblastoma (2); thyroid cancer (2); acute myeloid leukemia (1); adenoma (1); Alzheimer disease (1); amyotrophic lateral sclerosis (1); Anxiety (1); Ataxia (1); atypical teratoid rhabdoid tumor (1); Autoimmunity (1); cervical cancer (1); cervical neoplasms (1); Chronic Myelogenous Leukemia (1); colon adenocarcinoma (1); craniopharyngioma (1); dementia with Lewy bodies (1); ependymoma (1); esophageal cancer (1); esophageal squamous cell carcinoma (1); gastric adenocarcinoma (1); gliosarcoma (1); hematologic cancers (1); hematologic neoplasms (1); Hypertension (1); intestinal cancer (1); kidney cancer (1); Lewis lung carcinoma (1).
A further 18 diseases each share a sentence with EPHA3 in 1 paper.